INS (insulin)
Diseases named in the same sentence as INS in open-access papers (continued):
Sharing a sentence is not in itself a finding about the gene and the disease.
Insulin resistance (continued). "Although the results of our study cannot fully explain the exact mechanism by which the accumulation of CER impaired insulin pathway, both short- and long-terms inhibition of SphK1 intensified the palmitate induced insulin resistance in L6 myotubes." (PMID 24376889, 2013). "Dexamethasone-induced insulin resistance has been employed extensively in studies on insulin signaling." (PMID 24194903, 2013). "Insulin resistance was estimated by the homeostasis model assessment according to formula of HOMA-IR = (fasting insulin* FPG)/22.5." (PMID 22731255, 2012). "This is due to the inability of their islets to further increase insulin secretion to compensate increased insulin resistance and increased hepatic glucose production." (PMID 22829877, 2012). "The precise molecular mechanisms underlying the pathogenesis of iron-overload-related diabetes have not been identified but the initial glucose abnormalities include insulin resistance and hyperinsulinaemia, followed by impaired insulin secretion." (PMID 22752055, 2012). "As expected from the glycemia and insulin levels, insulin resistance estimated as HOMA-IR was the lowest in HUFD compared to CD, HDSD and HRSD groups (p < 0.05)." (PMID 22754464, 2012). "Iron reduction by phlebotomy also enhanced insulin sensitivity in patients with iron-induced insulin resistance and in carriers of the hemochromatosis gene." (PMID 22647517, 2012). "Visfatin levels were correlated positively with body mass index, waist/hip ratio, insulin, and homeostasis model assessment for insulin resistance and negatively with glucose/insulin ratio in the combined group (obese subjects plus controls)." (PMID 22672864, 2012). "Type 2 diabetes is characterized by impaired glucose homeostasis due to defects in insulin secretion, insulin resistance and the incretin response." (PMID 23056280, 2012). "Progression of T2D places increased demands on pancreatic β-cells for insulin production in order to compensate for spreading insulin resistance." (PMID 24278747, 2012). "In obesity or T2D, there is decreased ability of insulin to clear circulating glucose, defined as insulin resistance." (PMID 22848385, 2012). "In patients with metabolic syndrome, ghrelin was inversely correlated with insulin level and insulin resistance measured by HOMA-IR." (PMID 23029165, 2012). "The fasting glucose and insulin values were used to estimate the degree of insulin resistance with the homeostatic model assessment of insulin resistance (HOMA-IR)." (PMID 22682228, 2012). "Not only is there insulin resistance in T2DM, but there is also a loss of the early phase insulin secretion leading to persistent hyperglycemia secondary to the inability to suppress both glucagon secretion and hepatic glucose output." (PMID 23198247, 2012). "Central to this defect is insulin resistance, which reflects impaired sensitivity of target organs—primarily liver, pancreas, adipose tissue, and muscle—to insulin." (PMID 22110478, 2012). "The exposure of liver to such large quantities of fructose leads to rapid stimulation of lipogenesis and triglyceride accumulation, which in-turn contributes to reduced insulin sensitivity and hepatic insulin resistance/glucose intolerance." (PMID 24250458, 2012). "Insulin sensitivity is known to be a critical modulator of the insulin response to a stimulus, with insulin resistance increasing insulin release." (PMID 22876749, 2012). "Reduction in insulin level and insulin resistance in metformin groups was significant after treatment." (PMID 25246913, 2012). "The HNF-1α G319S polymorphism is associated in vitro with low insulin secretion, which allows expression of T2DM in the children who require physiological hyperinsulinemia to overcome differing degrees of insulin resistance." (PMID 22288007, 2012).
Insulin resistance (continued). "It is thought that genetically, insulin secretion compensation for insulin resistance is weaker in the Japanese than in Caucasians, and thus, being mildly overweight also conveys a risk factor for diabetes in Japan." (PMID 22364391, 2012). "The results clearly show that L. laricina decreased hyperglycemia and insulin resistance and improved mitochondrial function in the treatment study, while partially modulating parameters involved in insulin sensitivity in the prevention one." (PMID 22888363, 2012). "Estimated insulin resistance indicated that already after 9 weeks on the HF diet the HF mice were more insulin resistant than the LF mice and that a significant positive effect of running was seen in both diet groups." (PMID 22682013, 2012). "Insulin levels and insulin resistance were also shown to have improved after 3 months of intervention." (PMID 23304216, 2012). "During development of type 2 diabetes, insulin-producing β-cells initially compensate for the insulin resistance by enhanced insulin secretion, resulting in high circulating insulin levels." (PMID 23049932, 2012). "Due to insulin-sensitizing effects of adiponectin in humans, its plasma levels are inversely correlated with insulin resistance in type 2 diabetes (T2D)." (PMID 22272381, 2012). "It has recently been reported in chronic obstructive pulmonary disease that obese patients showed insulin resistance, whereas cachectic patients remain insulin sensitive." (PMID 23781298, 2012). "Iron deposition also induces insulin resistance by inhibiting glucose uptake in fat and muscle tissues, and reducing the capacity of liver to extract insulin, which results in an abnormal increase in hepatic glucose production." (PMID 22848554, 2012). "Because adipose tissue, muscle and liver are all major insulin-sensitive tissues that contribute to systemic insulin resistance by modulating insulin action, gene expression of C5L2, the ASP receptor, in adipose tissue, muscle and liver was evaluated." (PMID 23056509, 2012). "The changes in FBS, insulin,Homeostasis Model Assessment Insulin Resistance (HOMA-IR), hcy, hs-CRP and diastolic blood pressure before and after Ramadan were not significant (P >0.05, t test)." (PMID 22963582, 2012). "Some downstream intermediates in the insulin signaling pathways govern glucose homeostasis and can lead to skeletal muscle insulin resistance in T2D." (PMID 23028558, 2012). "The supplementation significantly (P < 0.01) decreased serum glucose, insulin, and insulin resistance as compared with hypertensive control." (PMID 22953063, 2012). "Reports have suggested that deregulated ubiquitin/proteasome-mediated degradation of insulin signaling molecules results in insulin resistance and the development of diabetes." (PMID 22110478, 2012). "Nevertheless, it is also worth mentioning that some studies have associated fructose consumption or feeding with elevated glucose, impaired glucose tolerance, elevated insulin concentrations, decreased insulin sensitivity and insulin resistance." (PMID 22337138, 2012). "The T-allele was also associated with lower fasting insulin and homeostasis model assessment index of insulin resistance in Whitehall-II and with lower post-load insulin after an oral glucose tolerance test in EARSII (all p < 0.05)." (PMID 21917432, 2012). "High-fructose feeding, as expected, induced insulin resistance and related blood indices, such as increased serum insulin level, the HOMA-IR index, and serum triacylglycerol concentration by 188, 240, and 63 %, respectively." (PMID 23065486, 2012). "Although not a universal finding, IL-6−/− mice have been shown to develop age-associated insulin resistance and when fed a HFD become markedly more insulin resistant than WT controls." (PMID 23240005, 2012).
Insulin resistance (continued). "In humans, the decline of gluco-regulatory functions and insulin resistance occur in the great majority of elderly, with the states of glucose intolerance due in part to a decline in peripheral tissue sensitivity to insulin." (PMID 22479589, 2012). "In fact, insulin as well as hyperinsulinemic rat serum after generation of high fat diet-induced insulin resistance promoted growth of androgen-independent prostate cancer PC-3 cells." (PMID 22891897, 2012). "It is well-known that both traits, insulin resistance and type 2 diabetes are strongly influenced by genetics with an estimated heritability for insulin resistance of around 60% and around 35–54% for the plasma insulin levels in familial and twin studies." (PMID 22396741, 2012). "In ARIC and JHS only, we assessed the association of African ancestry to hemoglobin A1c (HbA1c), fasting glucose and insulin level, and insulin resistance, which was estimated by the homeostasis model assessment (HOMA-IR)." (PMID 22438884, 2012). "It is known that insulin resistance increases with age and that normal blood glucose levels are maintained until the body is able to provide an adequate amount of insulin (hyperinsulinemia)." (PMID 22701480, 2012). "T2DM is a multifactorial disease in which genetic, environmental and lifestyle factors induce insulin resistance and impaired insulin secretion, ultimately leading to chronic hyperglycemia and its complications." (PMID 22675355, 2012). "It results from insulin resistance, a condition in which cells fail to use insulin properly, sometimes combined with an absolute insulin deficiency." (PMID 22257465, 2012). "In contrast, mTOR inhibition during rapamycin application leads to insulin resistance, reduces β-cell function and mass, limits insulin secretion, and results in DM." (PMID 22545721, 2012). "Insulin resistance was evaluated by oral glucose tolerance test, insulin tolerance test, and uptake of 2-[3H] deoxy-D-glucose in white adipose tissue." (PMID 23155382, 2012). "Telmisartan is a well-established angiotensin II type 1 receptor blocker that improves insulin sensitivity in animal models of obesity and insulin resistance, as well as in humans." (PMID 23137106, 2012). "Further, changes in glucose, insulin, and lipid homeostasis are characteristic of insulin resistance, type II diabetes, and metabolic syndrome." (PMID 22007192, 2012). "Insulin resistance can promote the development of atherosclerosis through elevated glucose and insulin concentrations, but also through mechanisms that involve dyslipidemia, hypertension, and inflammation." (PMID 23300589, 2012). "Upon binding to the complex of CD14 and toll-like receptor 4 on the surface of innate immune cells, LPS can induce systemic inflammation, which eventually impairs insulin sensitivity and induces insulin resistance-related metabolic disorders." (PMID 22880019, 2012). "Adult onset type-2 diabetes (T2DM) constitutes over 90% of all diabetes cases and is characterized by insulin resistance, abnormal insulin secretion, or both." (PMID 22524730, 2012). "In many patients with insulin resistance, insulin sensitizers, such as metformin and thiazolidinediones, have shown improving effect of liver biochemistry." (PMID 22701799, 2012). "As pregnancy is characterised by progressive insulin resistance from mid pregnancy (∼50–60% increase), maintenance of normoglycemia requires the pancreatic β-cells to compensate by appropriately increasing their insulin secretion." (PMID 23028837, 2012). "To investigate the mechanism of this effect, we examined the effect of HCQ on insulin resistance, insulin sensitivity, and pancreatic β-cell secretion of insulin in non-diabetic, obese subjects." (PMID 22676348, 2012). "It has been suggested that insulin resistance is associated with dysregulation of the PDC in skeletal muscle and that excess insulin would on the other hand down-regulate the expression of PDK4." (PMID 22682013, 2012).
Insulin resistance (continued). "Adiponectin has anti-inflammatory and insulin-sensitizing properties, and low adiponectin levels precede development of insulin resistance and T2D." (PMID 23396303, 2012). "For instance, mice lacking glutathione peroxidase 1 (Gpx1), characterized by increased insulin sensitivity, were protected from high-fat-diet-induced insulin resistance." (PMID 23443131, 2012). "Type 2 diabetes is the most common form of the disease, and the combination of insulin resistance in peripheral tissues and impaired insulin secretion from pancreatic β cells is believed to contribute to the development and progression of type 2 diabetes." (PMID 23029454, 2012). "In an attempt to overcome the reduction in insulin activity that occurs during insulin resistance, the number of β cells increases, resulting in a compensatory hypersecretion of insulin." (PMID 22110478, 2012). "The proposed mechanisms for such a potential link include insulin resistance, increased insulin level, increased glucose or triglycerides, obesity and increased level of thyroid-stimulating hormone (TSH)." (PMID 23300866, 2012). "Prevalence of type II diabetes, in which the body attempts to compensate for insulin resistance by augmenting insulin secretion, has increased because of the rising rate of obesity." (PMID 21977023, 2012). "In order to further explore the mechanism by which chromium picolinate induces insulin resistance, we used a human insulin signaling pathway PCR array to examine the expression of genes in skeletal muscle before and after chromium therapy." (PMID 23194380, 2012). "Three of five randomized trials demonstrate improvements in insulin sensitivity with vitamin D supplementation in subjects with insulin resistance or impaired fasting glucose." (PMID 22462011, 2012). "The HOMA-IR is easily calculated from fasting insulin and glucose levels and is commonly used for the evaluation of insulin resistance in clinical practice." (PMID 23249601, 2012). "Further, it is clear that insulin resistance can be reduced by regular exercise even in obese or insulin-resistant people when performed over several weeks or months." (PMID 22666560, 2012). "Previous studies have shown that an increase in plasma insulin by itself can induce insulin resistance." (PMID 23308073, 2012). "We argue this because in renin knockout mice, the metabolic phenotype of increased insulin sensitivity and resistance to high-fat diet-induced glucose intolerance and insulin resistance was reversed by Ang II infusion." (PMID 23308073, 2012). "Homeostasis model of insulin resistance (HOMA-IR) was calculated as [fasting insulin (μU/mL) × fasting glucose (mmol/L)/22.5]." (PMID 23351558, 2012). "Some previous studies have demonstrated that HOMA-IR strongly correlates with glucose clamp–assessed insulin resistance and has the advantage of requiring only a single plasma sample assayed for insulin and glucose." (PMID 23020992, 2012). "Insulin resistance and increase in insulin levels resulted from resistance to it and also other components of metabolic syndrome including: glucose intolerance, lipid disorder and increase in blood pressure is common in PCOS." (PMID 25246913, 2012). "These include increased fat oxidation and attenuation of adiposity and obesity, augmentation of insulin sensitivity and reversal of insulin resistance, and attenuation of systemic inflammatory stress." (PMID 22913271, 2012). "We found that PNU-282987 treatment improved insulin sensitivity in AMPKα2−/− mice, an animal model of insulin resistance." (PMID 23251458, 2012). "On PubMed search using Keywords “Migraine” and “Metabolic syndrome/insulin resistance/insulin metabolism” revealed six articles; two on metabolic syndrome and four on insulin metabolism in migraine." (PMID 22278639, 2012). "Increased basal pAKT is considered as a trigger of insulin resistance by desensitizing insulin signaling." (PMID 22412882, 2012).
Insulin resistance (continued). "Increased expression of PTP1B is associated with insulin resistance in rodents and humans whereas deletion of PTP1B leads to leanness and insulin sensitivity in rodents." (PMID 23028558, 2012). "Although myriocin treatment prevented the development of insulin resistance and improved skeletal muscle insulin signaling in db/db mice cardiac insulin signaling itself was not impaired in db/db versus db/+ mice (data not shown)." (PMID 22629445, 2012). "Adiposity markers were strongly correlated with insulin, insulin resistance, triglyceride, LDL-cholesterol and blood pressure in all population groups (data not presented)." (PMID 22558399, 2012). "In experimental and clinical settings, TZDs decrease insulin resistance, in part through their effect of decreasing the ratio of leptin to adiponectin, which are two important adipokines involved in appetite control and insulin sensitivity, respectively." (PMID 22235232, 2012). "These cytokines are increased in obesity and have multiple effects on insulin sensitivity in muscles, liver, or beta cells of the pancreas, ultimately leading to insulin resistance." (PMID 22550485, 2012). "After adjusting for the effect of insulin resistance on insulin secretion, the difference in HOMA2 disposition index based on 25OHD concentration was not significant." (PMID 22247968, 2012). "Injection of specific NOD1 ligand in mice promoted adipose tissue inflammation and induced whole-body insulin resistance with a strong decrease in insulin action in the liver." (PMID 23316186, 2012). "In the setting of insulin resistance, insulin is unable to properly suppress lipolysis in adipose tissue, resulting in a relative increase in free fatty acid release into the plasma." (PMID 23193424, 2012). "There is evidence that HCV itself can induce insulin resistance through changes in the route of insulin signaling and the entry of glucose into the cell." (PMID 22830036, 2012). "Skeletal muscle is the main tissue responsible for the insulin-stimulated disposal of glucose and is the main contributor to the development of insulin resistance in type 2 diabetes." (PMID 22353542, 2012). "Accordingly, the involvement of insulin resistance and high androgen levels in the molecular defects of the insulin cascade cannot be discarded." (PMID 22390153, 2012). "At 0, 4 and 7 wk from the start of the study insulin sensitivity was calculated by homeostasis model assessment of insulin resistance (HOMA-IR) and adiposity was determined by dual-energy X-ray absorptiometry (DXA)." (PMID 23098187, 2012). "These facts and the obtained results indicate that our assay with palmitic acid-induced insulin resistant L6 myotubes is suitable to screen for compounds that can induce or prevent insulin resistance." (PMID 22409911, 2012). "Insulin resistance is a state in which normal amount of insulin produces a subnormal physiological response." (PMID 22278639, 2012). "Subsequent insulin tolerance tests demonstrated more severe insulin resistance in the DKO mice, when compared to wild-type mice." (PMID 22792179, 2012). "Even in the insulin resistance stage, S. dulcis-treated L6 myotubes were found to be more capable of stimulating glucose transport than insulin treatment." (PMID 22474496, 2012). "In contrast, animals over expressing CD36 in muscle exhibited decreased plasma concentrations of triglycerides and increased plasma insulin and glucose concentrations and CD36 deficiency induced insulin resistance in the liver of these animals." (PMID 22662181, 2012). "A dysfunction in the incretin/anti-incretin system, for example the overproduction of anti-incretins, would result in decreased insulin secretion, decreased insulin action (insulin resistance) and a depletion in β-cell mass, leading to type 2 diabetes." (PMID 23133447, 2012).